TMEM132D (transmembrane protein 132D)
Description:
Regulate neuronals morphology via inhibition of the WAVE regulatory complex (WCR), a complex that controls F-actin cytoskeletal dynamics.
Synonyms: KIAA1944; MOLT; PPP1R153
Tractability: Antibody: UniProt predicts a signal peptide or a membrane-spanning region. PROTAC: ubiquitination databases record sites on it.
Gene: Protein-coding gene on chromosome 12 (129,071,725 to 129,904,025, reverse strand). Ensembl gene ENSG00000151952.
Subcellular location: Membrane
Gene Ontology:
Molecular function: protein binding
Cellular component: membrane
Genetic constraint (gnomAD): Loss-of-function variants: 21 observed, 60.49 expected, observed/expected ratio (o/e) 0.35, 90% interval 0.25 to 0.5. The upper end of that interval is the gene's LOEUF score, 0.5, which puts it in group 2 of 6, group 1 being the genes least tolerant of losing a copy. Missense variants: 1,286 observed, 1,406 expected, observed/expected ratio (o/e) 0.91, 90% interval 0.87 to 0.96. Synonymous variants: 600 observed, 578.86 expected, observed/expected ratio (o/e) 1.04, 90% interval 0.97 to 1.11.
Homologues: Orthologues: chimpanzee TMEM132D (99% identical), macaque TMEM132D (97% identical), pig TMEM132D (86% identical), dog TMEM132D (83% identical), rat Tmem132d (83% identical), mouse Tmem132d (83% identical), rabbit TMEM132D (71% identical), zebrafish TMEM132D (42% identical), Drosophila melanogaster dtn (27% identical), Caenorhabditis elegans tmem-132 (18% identical), tropical clawed frog tmem132a (17% identical). Paralogues in human: TMEM132C (61% identical), TMEM132B (50% identical), TMEM132E (39% identical), TMEM132A (31% identical).
Diseases named in the same sentence as TMEM132D in open-access papers:
TMEM132D is named in the same sentence as 22 diseases in open-access papers, as found by Europe PMC text mining. Sharing a sentence is not in itself a finding about the gene and the disease. The quoted sentences say what the papers report.
panic disorder (11 papers, 2015 to 2025). An anxiety disorder characterized by multiple unexpected panic attacks with persistent concern of recurring attacks. "Genome Wide Association study (GWAS) has revealed that the transmembrane protein 132D (TMEM132D) is a gene of sensitive for panic disorder (PD)." (PMID 36032246, 2022). "An association between polymorphisms in the TMEM132D region and panic disorder was also reported in a Japanese population." (PMID 36231907, 2022). "TMEM132D is a human gene identified with multiple risk alleles for panic disorders, anxiety and major depressive disorders." (PMID 33726789, 2021). "The human genome encodes 5 paralogs (TMEM132A-E), genetic variants of which have been identified as risk alleles of many human diseases, including those associated with panic disorder and anxiety severity in TMEM132D." (PMID 33726789, 2021). "Other members of the TMEM gene family, TMEM132E and TMEM132D genes are associated with bipolar and panic disorders, respectively, while TMEM231 is a known syndromic autism gene." (PMID 31323913, 2019). "TMEM132D is a candidate gene, where risk genotypes have been associated with anxiety severity along with higher mRNA expression in the frontal cortex of panic disorder patients." (PMID 29317594, 2018). "In case L, we identified a duplication of TMEM132D, a gene implicated in panic disorder, and thought to contribute to anxiety phenotypes." (PMID 27777633, 2016). "We herein report an association between TMEM132D and panic disorder (PD) in a Japanese population, evaluating the effects of HLA-DRB1*13:02, which we previously reported as a susceptibility genetic factor for PD." (PMID 27081567, 2016). "We found that lower methylation level of the CpG island site of TMEM132D is significantly related to panic disorder, and thus may increase the risk of panic disorder." (PMID 36032246, 2022). "Additionally, two other members (TMEM132E and TMEM132D) are known to be associated with bipolar and panic disorders." (PMID 31323913, 2019). "TMEM132D is more expressed in the cortical regions of the human brain and single-nucleotide polymorphisms (SNPs) (rs11060369, rs7309727) have been associated with panic disorder (PD) and anxiety severity." (PMID 29317594, 2018). "Furthermore, TMEM132D, encoding for a transmembrane protein, has already been associated with many neurological disorders such as anxiety and panic disorders and general behavioral disinhibition, including alcohol consumption and dependence, illicit drug use, and nicotine use." (PMID 41219721, 2025). "These included: rs61739178 on chromosome 7, a missense variant in COBL with a reported role in neuron morphogenesis and axon/dendrite branching; and rs937529 on chromosome 12, upstream of panic disorder and spinocerebellar ataxia 23 gene TMEM132D." (PMID 39454566, 2025). "The methylation of CpG2 of TMEM132D was shown to have a fully mediating effect between panic disorder and physical abuse." (PMID 36032246, 2022). "The current research still does not clearly show how the types of childhood abuse are related to TMEM132D and panic disorder." (PMID 36032246, 2022). "At the same time, TMEM132D methylation at CpG2 has a fully mediating effect between panic disorder and physical abuse." (PMID 36032246, 2022). "It is worth noting that the results of this study also indicate that TMEM132D methylation has a fully mediating effect between panic disorder and physical abuse." (PMID 36032246, 2022). "When an individual suffers more physical abuse, the methylation level of CpG2 on TMEM132D may enhance expression, which affects the occurrence of panic disorder." (PMID 36032246, 2022). "This conclusion suggests that hypo-methylation at the promoter region of TMEM132D may be a potential mechanism of panic disorder." (PMID 36032246, 2022). "The interaction between TMEM132D methylation and physical abuse can predict panic disorder." (PMID 36032246, 2022).
panic disorder (continued). "Dysfunction or dysregulation of TMEM132D may thus lead to abnormal neuronal structure and dynamics, contributing to heightened risks for depression, anxiety and panic disorders." (PMID 33726789, 2021). "Our study also demonstrated that methylation level of the CpG2 site in the promoter region of the TMEM132D plays a fully mediating role in the process of physical abuse on PD symptoms, thus suggesting its further application in early intervention and treatment of panic disorder." (PMID 36032246, 2022).
Anxiety (8 papers, 2016 to 2026). Intense feelings of nervousness, tension, or panic often arise in response to interpersonal stresses. "TMEM132D has been associated with anxiety phenotypes, aligning with neuroendocrine pathways that influence adiposity and lipid homeostasis." (PMID 41512839, 2026). "TMEM132D (transmembrane protein 132D) is primarily known for its association with addiction and anxiety." (PMID 38483771, 2024). "In healthy individuals, some of the TMEM132D non-coding variants exhibit higher anxiety scores and larger volumetric estimates of the amygdala and hippocampus, key neural structures associated with fear and anxiety." (PMID 29088312, 2018). "Risk variants of TMEM132D have been shown to correlate with altered mRNA levels of TMEM132D in anxiety-related brain regions and psychiatric syndromes." (PMID 33726789, 2021). "Similarly, Tmem132d mRNA is higher expressed in the aCC of high (HAB) compared to low (LAB) anxiety-related behavioral mice." (PMID 29317594, 2018). "The goal of this study was first to dissect the functional and molecular mechanism underlying differential expression of the Tmem132d gene, and further to investigate gene–environmental interactions in the context of EE and UCMS in the HAB/LAB mouse model of anxiety-related behavior." (PMID 29317594, 2018). "Furthermore, in cattle the TMEM132D locus appears to have undergone a selective sweep during domestication, and in the mouse, anterior cingulate cortex TMEM132D expression correlates with anxiety-related behaviour." (PMID 29088312, 2018).
small cell lung carcinoma (3 papers, 2021 to 2026). Small cell lung cancer (SCLC) is a highly aggressive malignant neoplasm, accounting for 10-15% of lung cancer cases, characterized byrapid growth, and early metastasis. "Mutations in the TMEM132D gene were found in pancreatic cancer and small cell lung cancer." (PMID 36900421, 2023). "TMEM132D and DNAH9 are cancer-associated genes in small cell lung cancer, and FDZ10 has a role in cancer reactivation." (PMID 33047283, 2021). "An early study indicated that TMEM132D was commonly mutated in small-cell lung cancer (SCLC) without being influenced by the stage, metastases, or chemotherapy treatment." (PMID 41596760, 2026).
breast cancer (2 papers, 2021 to 2023). A primary or metastatic malignant neoplasm involving the breast. "As a result, the combined model for TN breast cancer (TMEM132D, TMEM132C, MYO15B, S) demonstrated statistical significance (p = 0.0004) vs. the epigenetic model (TMEM132D, TMEM132C, MYO15B)." (PMID 36900421, 2023). "To further verify the identified target genes that showed significant changes in DE and DM patterns in response to the combination treatment, we evaluated the expression of Pdx1, Tmem132d, Get4, Rpl13 and Ndufa1 genes in mouse mammary tumors using qRT-PCR." (PMID 33947955, 2021). "For TN breast cancer, the inclusion of the clinical stage in the epigenetic classifier made it possible to achieve an area under the curve cvAUC = 0.87; 95% CI = 0.86–0.88 with a sensitivity of 0.71 and a specificity of 0.80 for the “TMEM132D, TMEM132C, MYO15B, S” panel." (PMID 36900421, 2023).
pancreatic cancer (2 papers, 2020 to 2023). "Somatic variants in the related factor TMEM132D have been found in small-cell lung and pancreatic cancer." (PMID 33680922, 2020).
frontotemporal dementia (1 paper, 2021). Frontotemporal dementia (FTD) comprises a group of neurodegenerative disorders, characterized by progressive changes in behavior, executive dysfunction and language impairment, as a result of degeneration of the medial prefrontal and frontoinsular cortices. "To our knowledge, TMEM132D has not been studied in the context of AD but we previously observed altered levels in patients with frontotemporal dementia." (PMID 33653397, 2021).
glioma (1 paper, 2017). A benign or malignant brain and spinal cord tumor that arises from glial cells (astrocytes, oligodendrocytes, ependymal cells). "FSTL5, HCN1, TMEM132D, TRHDE and KRT222 showed the strongest expression correlation with other genes in the co-expression network of glioma tissues." (PMID 29046615, 2017).
ovarian carcinoma (1 paper, 2015). A malignant neoplasm originating from the surface ovarian epithelium. "In the present study, we validated by qPCR the expression of two genes encoding the transmembrane proteins GPC6 and TMEM132D in a cohort of early stage ovarian cancer patients." (PMID 26448945, 2015). "For example, monitoring tumoral GPC6 and TMEM132D mRNA levels could facilitate the identification of early stage ovarian cancer patients at high risk." (PMID 26448945, 2015). "Thus, it is possible that the expression of TMEM132D is induced in ovarian cancer and by an unknown mechanism becomes implicated in CD8+ T-lymphocyte infiltration." (PMID 26448945, 2015). "We validated with qPCR the expression of GPC6 and TMEM132D in a cohort of stage I-II ovarian cancer patients." (PMID 26448945, 2015). "In this study, we documented an association between the expression of GPC6 and TMEM132D with CD8+ T-lymphocyte infiltration and favorable prognosis in early stage ovarian cancer." (PMID 26448945, 2015). "In order to validate the expression of GPC6 and TMEM132D in early stage ovarian cancer, we measured by qPCR their mRNA levels in tumor samples from 38 stage I-II ovarian cancer patients (resp)." (PMID 26448945, 2015). "To investigate whether GPC6 and TMEM132D expression correlates with CD8+ T-lymphocyte infiltration in early stage ovarian cancer, we used qPCR to quantify the mRNA levels of the CD8A marker in the same cohort of patients." (PMID 26448945, 2015). "In the present study, we evaluated the expression of two other overexpressed genes, GPC6 and TMEM132D, and investigated whether they could represent novel prognostic markers of survival in early stage ovarian cancer." (PMID 26448945, 2015). "Importantly, Kaplan-Meier survival analysis revealed that high mRNA levels of GPC6 and/or TMEM132D correlated significantly with increased overall survival of early stage ovarian cancer patients (p = 0.032)." (PMID 26448945, 2015). "GPC6 and TMEM132D expression was also documented in a variety of ovarian cancer cell lines." (PMID 26448945, 2015). "In conclusion, GPC6 and TMEM132D could serve as potent markers of CD8+ T-cell infiltration in early stage ovarian cancer." (PMID 26448945, 2015). "Thus, the mRNA expression levels of GPC6 and TMEM132D correlate with CD8+ T-lymphocyte infiltration in early stage ovarian cancer." (PMID 26448945, 2015). "Similarly, all ovarian cancer cell lines expressed TMEM132D." (PMID 26448945, 2015). "Ultimately, we performed a retrospective survival analysis of the early stage ovarian cancer patients and correlated the mRNA levels of GPC6 and TMEM132D with the overall survival." (PMID 26448945, 2015). "More importantly, we showed that early stage ovarian cancer patients with high mRNA levels of at least one of the two genes, GPC6 and TMEM132D, exhibited increased overall survival compared to patients with low levels of both genes." (PMID 26448945, 2015). "Moreover, we quantified by qPCR the relative expression of GPC6 and TMEM132D in a variety of ovarian cancer cell lines and demonstrated that the expression of both genes is not restricted to the infiltrating immune cells and may actually originate from the tumor cells." (PMID 26448945, 2015). "Taken together, our data indicate GPC6 and TMEM132D as potential markers for CD8+ T-lymphocyte infiltration, favorable prognosis, and survival benefit in early stage ovarian cancer." (PMID 26448945, 2015). "According to our results, early stage ovarian cancer patients with low mRNA levels of GPC6 and TMEM132D exhibit significantly reduced overall survival compared to patients with high levels of GPC6 and/or TMEM132D." (PMID 26448945, 2015). "Therefore, we suggest that GPC6 and TMEM132D mRNA levels could serve as markers of CD8+ T-cell infiltration and survival prognosis in early stage ovarian cancer." (PMID 26448945, 2015).
ovarian carcinoma (continued). "Thus, GPC6 and TMEM132D may serve as predictors of CD8+ T-lymphocyte infiltration and as favorable prognostic markers in early stage ovarian cancer with important consequences for diagnosis, prognosis, and tumor immunobattling." (PMID 26448945, 2015).
Tinnitus (1 paper, 2022). Tinnitus is an auditory perception that can be described as the experience of sound, in the ear or in the head, in the absence of external acoustic stimulation. "In this study, we report a burden of missense and LSV in constraint regions and support CACNA1E, NAV2, and TMEM132D as new candidate genes that contribute to severe tinnitus." (PMID 36450758, 2022).
cancer (4 papers, 2015 to 2023). A tumor composed of atypical neoplastic, often pleomorphic cells that invade other tissues. "Our conclusions underscore the necessity to elucidate the molecular mechanism of GPC6 and TMEM132D involvement in T-cell infiltration and their impact on cancer progression and also highlight their possible importance as putative diagnostic/therapeutic targets." (PMID 26448945, 2015).
TMEM132D also shares sentences with these, for which no sentence is quoted: major depressive disorder (3 papers); depression (2); Obesity (2); anxiety disorder (1); autism (1); diabetic neuropathy (1); head and neck squamous cell carcinoma (1); liver cancer (1); neurological disorders (1); ovarian tumors (1); tumor (1); type 2 diabetes (1).